YBX1 (Y-box binding protein 1)
Diseases named in the same sentence as YBX1 in open-access papers (continued):
Sharing a sentence is not in itself a finding about the gene and the disease.
cancer (continued). "These insights highlight YBX1 as a promising biomarker and potential target for combination therapies in cancer treatment." (PMID 41346602, 2025). "YBX1, also referred to as YB-1, is essential for the progression and drug resistance of various cancers and interacts with numerous noncoding RNAs to influence their biological activities." (PMID 40520020, 2025). "YBX-1 can translocate into the nucleus and regulate cell proliferation, adhesion and cancer cell resistance through transcription." (PMID 41180455, 2025). "We demonstrated that the YBX1 is overexpressed in EC specimens and its overexpression correlated with poor prognosis, supporting an oncogenic role of YBX1 in cancer." (PMID 41560755, 2025). "Disrupting the ligand-receptor interaction (Ptn-Ncl), transcriptional regulation (Ybx1), or cytoskeletal dynamics (Stmn1) presents several avenues to reduce cancer cell motility, invasiveness, and metastasis." (PMID 39975141, 2025). "YBX1 plays a pivotal role in various cancers and immune-related diseases, contributing to tumor proliferation, metastasis, drug resistance, and immune evasion, making it a highly promising therapeutic target." (PMID 41346602, 2025). "In turn, the YBX1 and Myc axis is known to negatively affect cancer cell apoptosis, and YBX1 stabilizes Myc protein and allows enhanced Myc translation independent of the IRES when cells encounter stress." (PMID 40855961, 2025). "In recent years, accumulating evidence has highlighted the central role of YBX1 in cancer development and progression." (PMID 41346602, 2025). "Collectively, these studies highlight the diverse mechanisms by which lncRNAs collaborate with YBX1 to regulate cancer progression, warranting further investigation into these potential pathways." (PMID 40860198, 2025). "MIR22HG binds and stabilizes YBX1 protein, affecting cell survival and death signals in cancer cells." (PMID 40799245, 2025). "Previous research has established that YBX1 frequently functions as a binding protein for various lncRNAs, contributing to the progression of multiple cancers, including CRC." (PMID 40234937, 2025). "Y-box binding protein 1 (YBX1) is a multifunctional RNA-binding protein that plays a central role in cancer progression across diverse tumor types." (PMID 41346602, 2025). "Long non-coding RNAs (lncRNAs) interact with YBX1, influencing its function and contributing to cancer progression." (PMID 40799245, 2025). "YBX-1 is significantly overexpressed in a variety of cancer types and is associated with poor outcomes, especially in HCC, and YBX-1 can be used as a prognostic indicator for HCC." (PMID 41180455, 2025). "In summation, intervening in YBX1 function through drug and small molecule inhibitors presents novel strategies for treating various cancers." (PMID 40799245, 2025). "YBX1 has a well-known oncogenic activity, and some ncRNAs can interact with it influencing directly cancer progression." (PMID 40951838, 2025). "These interactions highlight the diverse mechanisms through which lncRNAs modulate YBX1 function, making them promising targets for cancer treatment and prognosis evaluation." (PMID 40799245, 2025). "YBX1 is closely related to the occurrence and development of various diseases, including malignant tumors." (PMID 40799245, 2025). "Long non-coding RNAs (lncRNAs) exert diverse effects on YBX1 function through epigenetic modification, transcriptional regulation, and other mechanisms, impacting the development and metastasis of various cancers." (PMID 40799245, 2025). "As a multifunctional transcription factor and RNA-binding protein, YBX1 plays a central role in tumor initiation, progression, drug resistance, and immune evasion across various cancer types, making it a promising therapeutic target." (PMID 41346602, 2025). "Collectively, YBX1 acts as a critical driver of cancer progression and therapeutic resistance, integrating epitranscriptomic regulation, RNA-protein interactions, and immune modulation." (PMID 41346602, 2025).
cancer (continued). "While TIEG1 and Y-box binding protein 1 (YB1) directly bind the EGFR promoter to regulate cancer progression, we demonstrate XBP-1s binds the EGFR promoter." (PMID 41191192, 2025). "Looking ahead, the future research trajectory and prospects for YBX1 entail the development of small molecule drugs or inhibitors targeting YBX1, offering a promising new avenue for cancer treatment strategies." (PMID 40799245, 2025). "As a multifunctional oncoprotein, overexpression of YBX1 has been frequently observed and is often correlated with unfavorable prognoses in human cancers." (PMID 40082414, 2025). "Conversely, YBX1 is overexpressed in most cancer cells, where it transcriptionally or translationally activates a number of oncogenes to promote proliferation, drug resistance, and metastasis." (PMID 40812419, 2025). "Several clinical trials have commenced addressing YBX1 for cancer treatment, and the burgeoning preclinical research on YBX1 inhibitors underscores its clinically significant implications." (PMID 38255791, 2024). "Exploration of RNA interference therapies, such as siRNA and antisense oligonucleotides, seeks to silence YBX1 expression, especially in YBX1-dependent cancers." (PMID 38255791, 2024). "Overall survival and YBX1 expression data for cohorts of male and female cancer patients obtained from freely available databases were analysed with a cox proportional hazard model with covariates of biological sex and YBX1 expression." (PMID 38538658, 2024). "Despite the growing body of research on YBX1, most existing reviews have primarily focused on its roles in cancer biology." (PMID 39727969, 2024). "This review aims to offer a comprehensive understanding of Y-box binding protein 1 (YBX1)’s multifaceted role in cancer by summarizing its significant functions in relation to cancer hallmarks." (PMID 38255791, 2024). "Despite the well-established role of YBX1 in cancer, certain aspects of its involvement in tumor-promoting inflammation, phenotypic plasticity, and interactions with the polymorphic microbiome remain uncertain." (PMID 38255791, 2024). "By thoroughly analyzing ALYREF and YBX1, we aim to provide a solid basis for the identification of novel biomarkers for the early diagnosis of cancer and the prognosis of therapy." (PMID 38238581, 2024). "ALYREF and YBX1 as members of m5C readers that have garnered increasing attention in cancer research." (PMID 38238581, 2024). "YBX1’s interaction with multiple proteins and lncRNAs facilitates cancer cell migration, invasion, and metastasis in various cancers." (PMID 38255791, 2024). "Beyond ECM modulation, YBX1 exerts a profound impact on integrin signaling pathways within cancer cells." (PMID 38255791, 2024). "In recent years, targeted therapies against YBX1 and related agents have been developed and tested for cancer treatment." (PMID 39727969, 2024). "We suggested that the reason lies not only in the diversity of cancer types, but also in the molecular pathways through which YBX1 acts in autophagy." (PMID 39073262, 2024). "YBX1 acetylation at K301/304 links to inflammation and vascular damage, while K81 acetylation promotes YBX1 nuclear translocation, driving metastasis-related protein activation in cancer." (PMID 39727969, 2024). "While numerous studies support the oncogenic role of YBX1 in various cancers, promoting proliferation, migration, and chemoresistance, contrasting reports have emerged suggesting its tumor-suppressive functions." (PMID 38255791, 2024). "Taking into consideration the aberrant expression and prognostic value of ALYREF and YBX1 across cancers, we selected KIRP, LGG and LIHC as the main cancer types for further investigation." (PMID 38238581, 2024). "Its interaction with YBX1 significantly impacts CRC progression, stabilizing YBX1 and promoting aggressive cancer behavior." (PMID 38255791, 2024).
cancer (continued). "Through its regulatory effects on cellular senescence and immune responses, YBX1 contributes to the onset and progression of cancer and immune diseases, affecting their pathological characteristics." (PMID 39727969, 2024). "Existing research has primarily focused on YBX1’s impact on bone metastasis in other types of cancer, elucidating its role and mechanisms in promoting or suppressing metastatic processes in those contexts." (PMID 38255791, 2024). "YBX1 is a DNA/RNA binding protein that dysregulates a wide range of genes involved in cancer apoptosis, proliferation, differentiation, and drug resistance." (PMID 38491348, 2024). "In recent years, YBX1 has gained increasing attention in the field of cancer research due to its significant role in tumor initiation and progression." (PMID 38255791, 2024). "Numerous studies show that YBX1 can promote drug resistance and cancer progression through the AKT/mTOR pathway." (PMID 38849679, 2024). "These resources provide valuable insights into the molecular mechanisms and clinical diagnosis of ALYREF and YBX1, thus contributing to a more comprehensive understanding of m5C readers in cancer biology." (PMID 38238581, 2024). "The transcriptional regulation of YBX1 has been demonstrated to induce epithelial-mesenchymal transition (EMT) in various cancers." (PMID 38698857, 2024). "The expression level of YBX1 shows a significant positive correlation with CD4+ Th2 cells across twenty-six different cancer types." (PMID 38255791, 2024). "The multifunctional oncoprotein Y‐box‐binding protein‐1 (YB‐1) is frequently overexpressed in cancer and its inhibition reduces aggressive behavior in multiple tumor types." (PMID 36550787, 2024). "SETD8 serves as an unfavorable indicator of prognosis for ES patients, as it stimulates the growth of cancer cells and curbs both apoptosis and ferroptosis through the YBX1/RAC3 pathway." (PMID 38987564, 2024). "The potential of YBX1 in neurogenesis and its connection to neoneurogenesis also holds promise for future cancer research and application." (PMID 38255791, 2024). "Y-box binding protein-1 (YB-1) is a protein that plays multiple roles in regulating cancer markers and protecting against radiation-induced cell death." (PMID 39247603, 2024). "Y-box binding protein 1 (YBX1), a member of the Cold Shock Domain protein family, is overexpressed in various human cancers and is recognized as an oncogenic gene associated with poor prognosis." (PMID 38255791, 2024). "Some other studies suggest a significant role of YBX1 in facilitating DNA damage repair and maintaining genome stability, ultimately preventing cancer cells from succumbing to death signals." (PMID 38255791, 2024). "Lately, several molecules that influence cancer immunity by interacting with YBX1 have been identified." (PMID 38255791, 2024). "YBX1 is highly expressed in various cancers, and its expression level and cellular localization are closely associated with cancer progression, multidrug resistance, and poor prognosis." (PMID 39727969, 2024). "Y-box-binding protein 1 (YB-1) serves as an oncoprotein that plays a crucial role in cancer cell proliferation, stemness, DNA repair, and chemotherapy resistance." (PMID 38672529, 2024). "A large amount of research has been conducted on the role of YBX1 in cancers related to the brain and nervous system." (PMID 38255791, 2024). "YBX1 is an important contributor to tumorigenesis and is correlated with tumour stage and patient prognosis in cancer." (PMID 37929660, 2024). "The forest plot analysis of overall survival (OS) revealed a significant correlation between the expression of ALYREF, YBX1 and prognostic value across various cancers." (PMID 38238581, 2024). "Studies investigating the role of YBX1 in cancer metabolism have demonstrated its involvement in regulating glycolysis." (PMID 38255791, 2024).
cancer (continued). "Investigating the interplay between specific cancer types, subcellular localization, and post-translational modifications will likely yield a more nuanced understanding of YBX1’s multifaceted role in tumorigenesis." (PMID 38255791, 2024). "In the tumor microenvironment, CCL5 promotes cancer progression implying a connection between YBX1 and tumor-promoting inflammation." (PMID 38255791, 2024). "This comprehensive review elucidates YBX1’s multifaceted role in cancer across cancer hallmarks, both in cancer cell itself and the tumor microenvironment." (PMID 38255791, 2024). "We used available data for 15 cancer types to examine the link between YBX1 expression and survival outcomes." (PMID 38538658, 2024). "Accumulating evidence has indicated that YBX1 is a vital functional partner of multiple lncRNAs in cancer." (PMID 38491348, 2024). "Independent investigations have unveiled specific facets of YBX1’s contribution to cancer development." (PMID 38255791, 2024). "There have been many studies exploring the function of YBX1 in cancers, and the majority of scholars believe that it is an oncogene." (PMID 38182573, 2024). "Numerous studies have revealed the oncogenic function of YBX1, and some ncRNAs can interact with YBX1 to influence the progression of cancer." (PMID 38182573, 2024). "Initially, the expression levels of ALYREF and YBX1 were collected in 33 different types of cancers from the TCGA and GTEx databases." (PMID 38238581, 2024). "Leveraging the tumor-suppressive functions of cytoplasmic YBX1 in specific cancers represents a novel therapeutic avenue." (PMID 38255791, 2024). "Alternative approaches to target YBX1, with oligonucleotide-based methods such as siRNA and miRNA, along with virotherapy, show promise in cancer treatment." (PMID 38255791, 2024). "By elucidating the intricate mechanisms through which YBX1 influences various facets of cancer biology, we propose its potential as both a prognostic marker and a therapeutic target." (PMID 38255791, 2024). "YBX1’s context-dependent duality demands personalized therapeutic approaches, considering its varied roles across cancer types and cellular contexts." (PMID 38255791, 2024). "Such investigations will not only deepen our understanding of cancer biology but also hold significant potential for the development of innovative therapeutic strategies targeting YBX1 in cancer." (PMID 38255791, 2024). "YBX1 was considered to be a multifunctional oncoprotein and dysregulated a wide range of genes involved in cancer cell proliferation and survival, apoptosis, and drug resistance." (PMID 36805592, 2023). "Previous research in cancer cells has indicated that depletion of Ybx1 reduces cell growth and proliferation." (PMID 37378715, 2023). "Previous in vitro studies in human and mouse cancer cells have shown that Ybx1 knockout reduces cancer cell proliferation." (PMID 37378715, 2023). "Many reports point to YBX1 as a regulator of cellular proliferation, tumor metastasis and a determinant of cancer stem cell function in multiple cancer types." (PMID 36717896, 2023). "Our data from the clinical data analysis demonstrate that YBX1 expression is significantly higher in cancer stromal tissues." (PMID 38003589, 2023). "This study demonstrated that SATII RNA loading into sEVs is regulated via YBX1 and that YBX1 is a promising target in novel cancer therapy." (PMID 38003589, 2023). "The role of Ybx1 in cancer has been studied before, where Ybx1 is involved in the proliferation of tumor cells and is also considered a prognostic marker for malignant tumor growth." (PMID 37378715, 2023). "Given the recent studies reporting that YBX1 regulates autophagy in cancer cells and hepatic progenitor cells, we then assessed the function of YBX1 in autophagy in adipocytes." (PMID 36642732, 2023). "YBX1 was a versatile RNA‐binding protein that was highly overexpressed in multiple cancer types, and NDE1 and ERO1L were the two most DEGs." (PMID 35635121, 2023).
cancer (continued). "Nine of the ten papers published in this Special Issue explore various aspects of the multifunctional protein Y-box binding protein-1 (YB-1) and its role in cancer [...]." (PMID 37173888, 2023). "In previous studies, it has been reported that YBX1 promoted the growth of cancer stem cell population and seemed to modulate the expression of numerous stemness genes, including SOX2, CD10, CD24, and CD44." (PMID 36805592, 2023). "A previous report demonstrated that major satellite RNA, the mouse orthologue of pericentromeric SATII RNA, binds to Y-box binding protein (YBX1) and inhibits YBX1-mediated DNA repair, thereby contributing to cancer progression." (PMID 38003589, 2023). "Literature reports that YBX1 interacts with different lncRNAs and mediates some key processes in cancer." (PMID 36969033, 2023). "Y box binding protein 1 (Ybx1) is a DNA/RNA--binding protein is known to be involved in various types of cancers." (PMID 37059588, 2023). "Y box binding protein 1 (YBX1 or YB-1) is a versatile RNA-binding protein involved in multiple cellular pathways and linked with cancer progression." (PMID 36782290, 2023). "Emerging evidence showed that YBX1-mediated m5C was involved in cancer pathogenesis and development." (PMID 36642732, 2023). "Of note, while YBX1 promotes cancer cell proliferation and survival in many cancer types, it functions primarily to enhance metastasis in ccRCC, consistent its role in translational activation of Snai1 in ccRCC cells." (PMID 36028903, 2022). "In cancer cell lines, the transcription activity of YBX1 is controlled by the phosphorylation status of Ser residues 102 or 16546." (PMID 36241662, 2022). "Y-box binding protein-1 (YB-1) is a multifunctional protein that regulates the cancer hallmarks among them resisting to radiotherapy-induced cell death." (PMID 35989353, 2022). "Taken together, our data provide strong evidence for YBX1 acting as a cancer-specific modulator of translation in AML, while leaving total mRNA levels largely unaffected." (PMID 34465866, 2022). "Gene-dependency data from genome-wide CRISPR-Cas9 screens in over 700 cancer cell lines indicated a pan-cancer dependency only for YBX1." (PMID 34465866, 2022). "YBX1 codes for the Y- box binding protein-1, a multifunctional oncoprotein regulating cell proliferation, survival, drug resistance in cancer." (PMID 36060802, 2022). "YBX1, also known as YB-1, binds DNA and RNA, and it is closely related to various malignant phenotypes of cancer cells, including tumor cell proliferation, metastasis, angiogenesis, and drug resistance." (PMID 36289466, 2022). "The RNA-binding protein YBX1 (Y-Box Binding Protein 1) has emerged as an important driver in multiple cancers." (PMID 35406602, 2022). "LncRNA can form a positive feedback loop with YBX1 to activate the FOXA1 transcription network in cancer." (PMID 36169095, 2022). "For example, the lncRNA DSCAM-AS1 undergoes interaction with Y box binding protein 1 (YBX1), thereby promoting cancer growth by activating the forkhead box A1 (FOXA1) transcription network in a positive feedback loop." (PMID 35412951, 2022). "Mechanistically, the m5C methyltransferase NSUN2 and the m5C reader YBX1 drive cancer progression by targeting the m5C methylation site of the 3′ untranslated region of HDGF." (PMID 36532062, 2022). "In this regard, the Y-box binding protein-1 (YBX1) plays a role in cancer progression, having been described as being involved in the activation of MAPK/ERK (mitogen-activated protein kinase/extracellular regulated kinase) pathway." (PMID 35813211, 2022). "NPC is one of the HNSC with ethnic and geographical distribution preference; therefore, we searched the differential expression of YBX1 mRNA in 20 kinds of malignant tumors including HNSC by ONCOMINE database." (PMID 35260638, 2022).